OR13F1 (olfactory receptor family 13 subfamily F member 1)
Description:
Odorant receptor.
Synonyms: OR9-6
Tractability: Antibody: UniProt places it where antibodies can reach, with medium confidence; UniProt predicts a signal peptide or a membrane-spanning region; its Gene Ontology location is reachable by antibodies, with medium confidence.
Gene: Protein-coding gene on chromosome 9 (104,504,263 to 104,505,222, forward strand). Ensembl gene ENSG00000186881.
Subcellular location: Cell membrane
Pathways (Reactome):
Sensory Perception: Expression and translocation of olfactory receptors
Gene Ontology:
Molecular function: olfactory receptor activity; G protein-coupled receptor activity
Biological process: detection of chemical stimulus involved in sensory perception of smell; G protein-coupled receptor signaling pathway
Cellular component: plasma membrane; membrane
Genetic constraint (gnomAD): Loss-of-function variants: 1 observed, 1.66 expected, observed/expected ratio (o/e) 0.6, 90% interval 0.19 to 1.81. That is too few expected variants to judge how well the gene tolerates losing a copy. Missense variants: 386 observed, 403.85 expected, observed/expected ratio (o/e) 0.96, 90% interval 0.88 to 1.04. Synonymous variants: 142 observed, 157.32 expected, observed/expected ratio (o/e) 0.9, 90% interval 0.79 to 1.04.
Homologues: Orthologues: chimpanzee OR13F1 (96% identical), macaque OR13F1 (92% identical), rabbit OR13F1 (84% identical), dog OR13F1B (82% identical), dog OR13F1 (82% identical), rat Or13f5l1 (81% identical), mouse Or13f5 (80% identical), rat Or13f5 (79% identical), Caenorhabditis elegans ser-5 (18% identical), zebrafish adra2da (17% identical), zebrafish adra2db (16% identical), zebrafish adra1ab (15% identical). Paralogues in human: OR5T1 (44% identical), OR5T3 (42% identical), OR5T2 (41% identical), OR56A4 (31% identical), OR56A5 (30% identical), OR56A1 (30% identical), OR56A3 (29% identical), ADRA1B (19% identical), ADRA1D (18% identical), ADRA2A (17% identical), ADRA2B (17% identical), ADRA1A (17% identical), and 6 more.
Diseases named in the same sentence as OR13F1 in open-access papers:
OR13F1 is named in the same sentence as 2 diseases in open-access papers, as found by Europe PMC text mining. Sharing a sentence is not in itself a finding about the gene and the disease. The quoted sentences say what the papers report.
mitochondrial disease (1 paper, 2025). "Furthermore, we observed signals in important genes associated with ASD pathways, such as RGS3 in Cluster 24, encoding a regulator of G protein signaling; NUBPL in Cluster 25, previously associated with mitochondrial disease; and OR13F1 in Cluster 8, encoding an olfactory receptor." (PMID 40440618, 2025).
OR13F1 also shares sentences with these, for which no sentence is quoted: cancer (1 paper).